C9orf163 (chromosome 9 putative open reading frame 163)
Synonyms: FLJ36779
Gene: Long non-coding RNA gene on chromosome 9 (136,483,495 to 136,486,067, forward strand). Ensembl gene ENSG00000196366.
Diseases named in the same sentence as C9orf163 in open-access papers:
C9orf163 is named in the same sentence as 10 diseases in open-access papers, as found by Europe PMC text mining. Sharing a sentence is not in itself a finding about the gene and the disease. The quoted sentences say what the papers report.
breast carcinoma (2 papers, 2022 to 2024). "This study identified 11 key methylation-driven lncRNAs (DIO3OS, ELOVL2-AS1, MIAT, LINC00536, C9orf163, AC105398.1, LINC02178, MILIP, HID1-AS1, KCNH1-IT1, and TMEM220-AS1) closely associated with breast cancer prognosis through three machine learning methods." (PMID 39456830, 2024). "Furthermore, we found that the expression of USP30-AS1 and C9orf163 were associated with BRCA1/2 status, indicating that they were involved in breast cancer development." (PMID 36276952, 2022).
pancreatic cancer (2 papers, 2022 to 2023). "C9orf163 could develop the tumor microenvironment through cytokine and chemokine signaling and might act as a tumor suppressor in anaplastic gliomas and pancreatic cancer." (PMID 36276952, 2022).
tumor (2 papers, 2020 to 2022). "These suggest that C9orf163 might contribute to building tumor microenvironment via affecting cytokine and chemokine related signaling." (PMID 33061845, 2020). "These suggested LINC00476, c9orf163 and DSCR9 might act as tumor suppressors in PC." (PMID 33061845, 2020).
cancer (1 paper, 2022). A tumor composed of atypical neoplastic, often pleomorphic cells that invade other tissues. "Several DEGs identified were known to be involved in several cancers, these include the microRNA MIR-186 and the PPP1R1C genes, both of which were up-regulated in our study, and NGEF, C9orf163, INKA2-AS1 and SULT2B1 which were found to be downregulated." (PMID 36197921, 2022).
C9orf163 also shares sentences with these, for which no sentence is quoted: anaplastic gliomas (1 paper); colon cancer (1); head and neck squamous cell carcinoma (1); osteonecrosis (1); ovarian carcinoma (1); squamous cell lung carcinoma (1).